KRAS (KRas proto-oncogene, GTPase)
Diseases named in the same sentence as KRAS in open-access papers (continued):
Sharing a sentence is not in itself a finding about the gene and the disease.
adenocarcinoma (continued). "Scheel and colleagues demonstrated a strong association between mutations in KRAS with PD-L1 expression in adenocarcinoma specimens (OR = 2.5; p = 0.018)." (PMID 29464099, 2018). "Mutations in Kirsten rat sarcoma viral oncogene homolog (KRAS) were detected in 75% of IMAs, but in only 11.6% of conventional adenocarcinomas." (PMID 30513627, 2018). "EGFR mutations were associated with low- to intermediate-grade adenocarcinomas, and KRAS mutations were associated with the mucinous subtype." (PMID 29065153, 2017). "Only one ADC was KRAS mutated (representing 8% of adenocarcinomas) whereas KRAS mutations are reported in more than 30% of lung ADC, especially in smokers." (PMID 28619094, 2017). "In NSCLC, PD-L1 expression is the highest in squamous cell carcinoma of smokers and is related to solid subtype and KRAS mutation in adenocarcinoma." (PMID 28671973, 2017). "The distribution in our study was similar, except for KRAS mutations which seemed to be more frequent in advanced disease (29%), probably due to the higher incidence of adenocarcinoma." (PMID 28445990, 2017). "The 5.3% frequency of exon 14 MET mutations was derived from 150 adenocarcinomas carrying similar mean gene mutation frequencies as those previously reported in France for KRAS (23.3%), EGFR (9.3%), and BRAF (0.3%)." (PMID 28418914, 2017). "KRAS mutations were found in 19 of 19 patients with a preoperative cytological diagnosis of adenocarcinoma and 9 of 10 patients with atypical cells." (PMID 28125707, 2017). "Two KRAS-mutated adenocarcinoma cell lines (A549 and H441) were cultured and selected on ultra-low attachment culture dishes, and the resulting cells were defined as FL (for floating) sublines." (PMID 28786996, 2017). "KRAS mutations were the only independent prognostic factor in patients with resected stage I adenocarcinoma." (PMID 29065153, 2017). "We also analyzed correlations between CCDC106 expression and driver mutations, such as EGFR and KRAS, in adenocarcinoma tissues." (PMID 28460455, 2017). "Two patients with metastatic KRAS-mutated adenocarcinoma, where pseudo-progression was observed during anti-PD-1 treatment, were included in this study." (PMID 28445137, 2017). "It was generally reported that the KRAS gene mutations are more frequent in females, smokers and adenocarcinoma subtypes." (PMID 25902737, 2016). "In our study, we indicated the association between the KRAS gene mutations presence and smoking status as well as adenocarcinoma diagnosis." (PMID 25902737, 2016). "Factors such as large PTV and KRAS mutations in adenocarcinomas (all on codon 12) were found to be associated worse OS (p < 0.05)." (PMID 27611833, 2016). "The pyrograms now show that the adenocarcinoma is positive for KRAS G12C mutation and the neuroendocrine component is positive for KRAS G12D mutation." (PMID 27597976, 2016). "After microdissecting and testing the adenocarcinoma and neuroendocrine components separately, it was found that the adenocarcinoma was positive for KRAS G12C mutation and the neuroendocrine component was positive for KRAS G12D mutation." (PMID 27597976, 2016). "Regarding the adenocarcinoma groups the presence of KRAS mutations was more common in Invasive mucinous AdCa (5 out of 11 samples), but no statistical correlations were elicited." (PMID 26208325, 2015). "KRAS mutations were the most common alteration detected in our cohort accounting for 26.5% of the examined cases and correlated with adenocarcinoma histology." (PMID 26208325, 2015). "S100A11 levels were significantly higher in adenocarcinomas with KRAS mutations and strong proliferating activity (P = 0.038 in the Kruskal-Wallis test)." (PMID 26544866, 2015).
adenocarcinoma (continued). "Among the three subtypes, S100A11 levels were significantly higher in adenocarcinomas with KRAS mutations and strong proliferating activity." (PMID 26544866, 2015). "Adenocarcinoma is the most common histologic subtype of lung cancer and frequently carries a KRAS mutation (10–30% of cases)." (PMID 26193700, 2015). "Ten of 14 adenocarcinomas underwent molecular mutational profiling: 2/8 had KRAS mutation, 1/10 had EGFR mutation, and 0/5 had ALK rearrangement." (PMID 25689302, 2015). "These included resistant KRAS mutations (p.Gly12Cys and p.Gly12Val) in two of seven (29%) adenocarcinoma PDX." (PMID 25470237, 2015). "Mutation of KRAS is an early event in adenocarcinoma development, as it is found in atypical adenomatous hyperplasias and bronchoalveolar carcinomas." (PMID 26193700, 2015). "Concerning cases of ICC, mostly adenocarcinomas, 31% have a mutation in the KRAS gene and 21% have IDH 1 and 2 gene mutation." (PMID 25400964, 2014). "Different results were found in the study group compared to the ones in literature: among 16 mucus-secreting adenocarcinomas, 8 cases presented wild type KRAS gene and 6 cases presented codon 12 mutations and 2 cases presented codon 13 mutations." (PMID 25713627, 2014). "Adenocarcinoma cells with mutant KRAS and loss of LKB1 are also addicted to the mitochondrial metabolism driven by lysosomal degradation of macromolecules which, in turn, depends on coatomer complex 1 (COP-1)." (PMID 24722523, 2014). "Activation of the KRAS oncogene has been implicated in colorectal carcinogenesis, being mutated in 30–40% of adenocarcinomas, a prevalence comparable to that observed in the present study (42.85%)." (PMID 25412182, 2014). "Several studies have reported KRAS mutant signatures or differentially expressed genes between adenocarcinomas with EGFR and/or KRAS mutations and respective wild type cases." (PMID 24205279, 2013). "Several studies have reported genomic or transcriptional alterations between EGFR-mutated and/or KRAS-mutated tumors and corresponding wild-type adenocarcinomas." (PMID 24205279, 2013). "This conclusion appears consistent with the somewhat mixed inclusion of EGFR-mutated, KRAS-mutated and EGFRwt/KRASwt adenocarcinomas in different reported molecular subtypes of adenocarcinomas." (PMID 24205279, 2013). "The results also showed spontaneous loss of LKB1 expression in some KRas+/LSLG12Vgeo -induced adenocarcinomas (3 out of 12 tumors)." (PMID 23825589, 2013). "Taken together, these results suggest a higher genomic complexity in EGFR-mutated adenocarcinomas compared with KRAS-mutated and EGFRwt/KRASwt tumors." (PMID 24205279, 2013). "KRAS-mutated adenocarcinomas had a higher prevalence in females (P<0.001) and showed less frequent vascular invasion (P=0.018) in never smokers compared with heavy smokers." (PMID 24179496, 2013). "In summary, our multicohort analyses of genomic and transcriptional alterations demonstrate both differences and strong similarities between the EGFR and KRAS mutation defined adenocarcinoma groups." (PMID 24205279, 2013). "Since progression of adenocarcinoma can be driven by mutations to the KRAS oncogene, we analyzed the mutation hotspots at codons 12 and 13 of exon 2 using Sanger sequencing of PCR products." (PMID 23505554, 2013). "KRAS-mutated adenocarcinomas had a higher prevalence of females (P<0.001) and showed less frequent vascular invasion (P=0.018) in the never smokers compared with the heavy smokers." (PMID 24179496, 2013). "Differentially expressed genes between EGFR/KRAS mutation groups in ≥4 of five Affymetrix adenocarcinoma cohorts." (PMID 24205279, 2013). "Lower rates of mutations in the pre-operative cohort to that expected in a Caucasian NSCLC population were observed, with only four EGFR (4%) mutations and nine KRAS (9%) mutations, all occurring in adenocarcinomas as expected." (PMID 23935846, 2013).
adenocarcinoma (continued). "KRAS mutations were found in 277 out of 832 (33.3 %) tested patients; in 244/662 (36.9 %) adenocarcinomas." (PMID 22528563, 2012). "In 30% of adenocarcinomas, mutation of the KRAS proto-oncogene is the driving force behind oncogenic transformation, and similar mutations are found to a lesser extent (about 5%) in the squamous-cell carcinoma subtype." (PMID 22928112, 2012). "In our study KRAS mutations were found in 28.8%, predominantly in adenocarcinomas, and this is in accordance with published data." (PMID 26316935, 2012). "KRAS mutations were identified in 23 (17.5%) of fully analysed patient samples (18 adenocarcinoma and five NSCLC-NOS)." (PMID 21949883, 2011). "Fifty-six per cent of serrated adenocarcinomas with microsatellite stability/low-level microsatellite instability harboured KRAS mutations." (PMID 21457162, 2011). "Here we also performed a limited comparison of the ability of COLD-PCR to detect EGFR and KRAS mutations in 25 EBUS-derived adenocarcinoma cytological aspirates with that of standard-PCR." (PMID 21949883, 2011). "The high frequency of KRAS mutations in serrated adenocarcinomas further strengthens the importance of the colorectal serrated pathway." (PMID 21457162, 2011). "EML4-ALK fusion occurs in a mutually exclusive fashion with EGFR or KRAS mutations and, almost exclusively, in adenocarcinomas." (PMID 21785682, 2011). "This is the first study to show that KRAS mutations are frequent (45%) in serrated adenocarcinomas, and that the MAPK activation resulting from either KRAS or BRAF mutations is very common (79%) in serrated adenocarcinomas." (PMID 21457162, 2011). "A high frequency of KRAS mutations in serrated adenocarcinomas suggests that a significant proportion of KRAS-mutated CRCs originate from serrated precursors, thus challenging the traditional model of Vogelstein." (PMID 21457162, 2011). "Mutations of KRAS also target adenocarcinoma histology, but otherwise differ from EGFR mutations because they are relatively rare in East Asians and occur more frequently in males and smokers." (PMID 19238210, 2009). "For 45 adenocarcinomas having SNP array data, direct sequencing detected a high frequency of KRAS (n = 21, 47%) or EGFR (n = 14, 31%) mutations." (PMID 19826477, 2009). "Because approximately 40% of adenocarcinomas in ex- and current smokers show mutated-type KRAS (especially if poorly differentiated), erlotinib use here should be a cautious last resort." (PMID 19672420, 2009). "The second responding patient with a KRAS mutation (Pt 7) was a 52-year-old woman who had been treated in June 1999 for a primary adenocarcinoma of the rectum classified pT4N2." (PMID 18544172, 2008). "Within the adenocarcinoma subset, the KRAS mutation rate was 32.4%." (PMID 40563596, 2025). "Adenocarcinoma was the predominant subtype (95%), and KRAS mutations were found in 90%." (PMID 40314773, 2025). "The adenocarcinoma component showed an exclusive amplification of KRAS as well as a SMAD4 mutation." (PMID 40833530, 2025). "For example, EGFR mutations have been associated with a predilection for brain involvement in adenocarcinoma, while KRAS mutations may favor hepatic spread." (PMID 41294679, 2025). "When adenocarcinomas were analyzed separately, the KRAS and TLS association receded." (PMID 40029549, 2025). "All tumors containing an EGFR mutation and 91.1% of KRAS mutated cases were adenocarcinomas." (PMID 40591555, 2025). "Data in relevant mouse models of KRAS mutant/STK11 deficient adenocarcinoma fully supported this hypothesis." (PMID 40069402, 2025).
adenocarcinoma (continued). "We hypothesize that factors such as unanalyzed KRAS mutation, parameter differences between the two central machine models, possible fat interference within adenocarcinoma (MC and AC), and selection bias may lead to the variability of APT values." (PMID 40458716, 2025). "Adenocarcinoma cases had a higher prevalence of SNVs, CNVs, and/or fusions/rearrangements in 28 genes including therapy-associated genes such as KRAS (37.5% vs 4.6%), EGFR (17.1% vs 1.3%), BRAF (5.2% vs 1%), ERBB2 (1.8% vs 0.8%), RET (0.9% vs 0.3%), and ROS1 (1.2% vs 0.1%)." (PMID 39664186, 2024). "Additionally, activating KRAS mutations are also found in adenocarcinomas more predominantly in the West (30%) than in Asia (10%)." (PMID 39513892, 2024). "The frequency of KRAS mutations also varies in the histological subtypes of adenocarcinoma." (PMID 38953007, 2024). "Adenocarcinoma was the most common histology among patients with a KRAS mutation (88%)." (PMID 37040387, 2023). "KRAS gene mutation results in different adenocarcinoma types." (PMID 37340599, 2023). "The KRAS mutation is highly detected in heavy-smoking patients, most of them with adenocarcinoma." (PMID 34636991, 2022). "Notably, KRAS mutations are more common in the adenocarcinoma histotype than in squamous NSCLC (20–40% and 5%, respectively) and most frequently found in smokers (30%) vs. non-smokers (11%) and in the Caucasian vs. Asian population (26% and 11%, respectively)." (PMID 35743191, 2022). "Up to 25–30% of adenocarcinoma cases have associated KRAS mutations." (PMID 36136862, 2022). "EGFR and KRAS mutations suggest a poor prognosis in adenocarcinoma patients." (PMID 35835908, 2022). "Most KRAS mutations (72.7%) were found in tumors with adenocarcinoma component." (PMID 35359599, 2022). "Interestingly, in more than 90% of PDAC tumors, the oncogene KRAS is mutated, and KRAS G12D is the predominant driver mutation in this type of adenocarcinoma." (PMID 36230869, 2022). "Adenocarcinoma histology was more frequent in patients with KRAS mutated tumors (80%)." (PMID 34413420, 2021). "Demonstration of a KRAS or NRAS mutation may be useful in diagnosing a mesonephric adenocarcinoma and distinguishing this from florid mesonephric hyperplasia, which does not exhibit mutations." (PMID 33570865, 2021). "Consistently with the literature, KRAS mutations predominated among the different appendiceal lesions: in fact, half of our cases showed KRAS point mutations and these mutations harboured in SSLs (about 60%) as well as in adenocarcinomas (44%)." (PMID 33712927, 2021). "However, targeting adenocarcinomas harboring mutations of the EGFR downstream substrate KRAS still remains a significant unmet clinical need in oncology." (PMID 34573384, 2021). "A large study in French CRC patients reported that KRAS mutants, KRAS exon 2 mutants, and KRAS codon 12 mutants were associated with the same clinicopathological features: male sex, classical adenocarcinoma, and well/moderately differentiated histological grade." (PMID 32628708, 2020). "The mutations most frequently reported in adenocarcinoma occur in the KRAS and EGFR genes." (PMID 32756609, 2020). "In this regard, the co-inhibition of FAK and BRD4 may lead to impaired activation of dynamics of T regulatory cell populations and IL8-linked NF-KB network in NSCLC adenocarcinomas, including those with KRAS mutations." (PMID 32793596, 2020). "Generally, around 30% of lung tumors—primarily adenocarcinomas—harbor a KRAS mutation." (PMID 33322500, 2020).
adenocarcinoma (continued). "Our analysis of the TCGA cohort showed that a subset of pro-tumorigenic integrins, including α1β1, α2β1, α3β1, α5β1, and α6β4, were frequently amplified or upregulated at the genomic or mRNA level in KRAS or EGFR mutation/overexpression-enriched adenocarcinomas." (PMID 32793596, 2020). "KRAS mutations are frequently found in adenocarcinomas of the lung, colon, and pancreas." (PMID 33023600, 2020). "EGFR and KRAS mutations in tissue was detected only in adenocarcinomas." (PMID 32196518, 2020). "Additionally, adenocarcinoma cell line A549, was a known KRAS mutated cell line and matches with data from patients with mutated KRAS, also showing FGF14 downregulation." (PMID 32707902, 2020). "In addition, two KRAS somatic mutations (Gly12Asp and Gly12Cys) were found in 2/23 adenocarcinoma LCs." (PMID 30925779, 2019). "However, a CDKN2A deletion in mutant KRAS-expressing mice prevented the progression to senescence and led to invasive and metastasizing adenocarcinomas with morphological and molecular features similar to KRAS-mutated adenocarcinomas." (PMID 29690599, 2018). "This is also the first report of somatic KRAS mutation in OSP-associated adenocarcinoma." (PMID 29879069, 2018). "All of the KRAS mutations detected were in adenocarcinoma specimens." (PMID 29673125, 2018). "KRAS mutations in NSCLC are detected more frequently in adenocarcinoma than SQ cell carcinoma." (PMID 28881686, 2017). "As ctDNA kinetics correlate with the response to treatment in KRAS-mutated adenocarcinoma, we anticipated that this analysis could be of interest." (PMID 28445137, 2017). "Among 115 adenocarcinoma cases, only 38 harbored a KRAS mutation, and 73 had an EGFR mutation." (PMID 28460455, 2017). "Combining the status of the Kirsten rat sarcoma viral oncogene homolog (KRAS) G12D (35G>A) mutation with the expression profiles of 69 genes associated with clinical prognosis classified the adenocarcinoma cells into four groups with different gene expression patterns." (PMID 28405930, 2017). "In our study, the KRAS mutation rate was extremely low in both the entire patient group (53 of 1033, 5.13%) and the adenocarcinoma patient group (45 of 759, 5.93%), which is consistent with a previous conclusion that Asians exhibit a lower frequency of KRAS mutations." (PMID 26739511, 2016). "KRAS mutations were significantly more frequent in adenocarcinoma patients and smokers." (PMID 25902737, 2016). "When the adenocarcinoma and neuroendocrine components were microdissected separately and tested separately for KRAS mutations, the adenocarcinoma component was found to harbor a KRAS G12C mutation, and the neuroendocrine component was found to harbor a KRAS G12D mutation." (PMID 27597976, 2016). "However, in the adenocarcinoma stage in which the KRAS mutation was added, the essentiality of MEK increased dramatically from 0.024 to 0.58." (PMID 27765040, 2016). "The second patient was a former smoker man with KRAS mutated advanced adenocarcinoma of the lung." (PMID 25955492, 2015). "In addition, our epidemiological results are in line with literature: KRAS mutations are strongly correlated with smoking habit and adenocarcinoma histology and are mutually exclusive with EGFR mutations." (PMID 26416458, 2015). "KRAS mutations distributed amongst different Adenocarcinoma groups." (PMID 26208325, 2015). "Stratification of identified mutations by IHC subgroup revealed a striking enrichment of oncogene mutations in adenocarcinoma-like LC tumors (85% of all oncogene mutations, affecting 63% of these cases), including all nine KRAS mutations and the single NRAS (G12D) and MAP2K1/MEK1 (K57N) mutations." (PMID 26124082, 2015).